HDAC8 (histone deacetylase 8)
Diseases named in the same sentence as HDAC8 in open-access papers (continued):
Sharing a sentence is not in itself a finding about the gene and the disease.
neuroblastoma (continued). "Recent studies indicated that HDAC8 inhibition induces differentiated phenotypes and reduces neuroblastoma growth in vitro and in vivo with few adverse effects." (PMID 32318119, 2020). "HDAC8 is either overexpressed or dysregulated in cancers, such as neuroblastoma, breast cancer, colon cancer and hematological malignancies." (PMID 33015043, 2020). "Investigations of the expression levels of classical HDACs across a large cohort of primary neuroblastoma samples also identified HDAC8 as a prognostic indicator of advanced disease stage and poor survival." (PMID 33117806, 2020). "Combined treatment of neuroblastoma cells with all-trans RA and an HDAC8 inhibitor resulted in enhanced tumor cell death." (PMID 30890583, 2019). "HDAC8 is an established target for T-cell lymphoma and neuroblastoma and overexpressed in other tumors." (PMID 30292946, 2019). "HDAC8, a class I zinc-dependent enzyme, is a potential drug target for treatment of neuroblastoma and T cell lymphoma." (PMID 31748509, 2019). "As an example, HDAC8 downregulation increases the sensitivity to doxorubicin therapy in neuroblastoma and induces the differentiation of malignant cells into neurons." (PMID 31798765, 2019). "A possible regulation of HDAC8 by redox signal transduction is suggested by the observed relationship between inhibition of reactive oxygen species generating NOX and concomitant increased HDAC8 activity in neuroblastoma tumor cells." (PMID 30292946, 2019). "Several studies confirmed that HDAC8 acts as an oncogene in different tumors, including gastric cancer, neuroblastoma, T-cell lymphocytes, hepatocarcinoma and breast cancer." (PMID 31798765, 2019). "The physiologically relevant regulation of HDAC8 by redox signal transduction is suggested by a clear connection between the activities of ROS/H2O2 generating NOX and HDAC8 in neuroblastoma tumor cells." (PMID 30292946, 2019). "The potential physiological relevance of redox-regulation of HDAC8 is demonstrated by the inhibition of endogenously produced H2O2 in neuroblastoma cells." (PMID 30292946, 2019). "We found that miR-665 suppresses mRNAs, targeting c-MYC and HDAC8, which are involved in neuroblastoma tumorigenesis." (PMID 30237861, 2018). "Since TH34 treatment induces hyperacetylation of SMC3 in high-grade neuroblastoma cells by blocking HDAC8, we investigated if nuclear morphology and abundance of intact and aberrant mitotic figures changed under TH34 treatment." (PMID 29947893, 2018). "HDAC8 overexpression correlated with advanced neuroblastoma in patient tumor samples, and HDAC8 inhibition reduced cell proliferation and induced neuroblastoma cell differentiation." (PMID 30237861, 2018). "The phosphorylation of AKT by HDAC8 inhibitor treatment is in line with the results of the initial RNAi screen, which indicated that the PI3K pathway mediates HDAC8 inhibitor anti-neuroblastoma effects." (PMID 29515255, 2018). "This is the first report demonstrating that miR-665 is a suppressor miRNA targeting both c-MYC and HDAC8, which are involved in neuroblastoma tumorigenesis." (PMID 30237861, 2018). "Our results strongly indicate that miR-665 upregulation decreased MYC and HDAC8 expression, thus inhibiting proliferation and inducing apoptosis in mouse neuroblastoma cells." (PMID 30237861, 2018). "Our laboratory is presently investigating the therapeutic effects of miR-665 and c-MYC- and HDAC8-specific siRNAs in transplanted mouse neuroblastoma tumors." (PMID 30237861, 2018). "HDAC8 inhibition synergizes with retinoic acid treatment to induce neuroblast maturation in vitro and to inhibit neuroblastoma xenograft growth in vivo." (PMID 29947893, 2018). "We identified receptor tyrosine kinases (RTKs), such as anaplastic lymphoma kinase (ALK), as druggable neuroblastoma cell survival activators that can be targeted by treatment with small molecule inhibitors, thus sensitizing neuroblastomas to HDAC8 inhibition." (PMID 29515255, 2018).
neuroblastoma (continued). "siRNA-mediated HDAC8 knockdown inhibited proliferation of human lung, colon, cervical cancer, and neuroblastoma cell lines." (PMID 30237861, 2018). "HDAC8 is the only HDAC that is significantly transcriptionally upregulated in high-grade (INSS stage 4) neuroblastoma patient samples as compared to prognostically favorable stage 1, 2, 3 and 4S tumors." (PMID 29947893, 2018). "Selective inhibition of HDAC8 slows neuroblastoma growth, induces a more differentiated phenotype and serves as a potent enhancer of retinoic acid-mediated anti-neuroblastoma activity both in vitro and in vivo." (PMID 29515255, 2018). "Accordingly, the co-expression of both genes, ALK and HDAC8, was correlated with poor survival of neuroblastoma patients in both cohorts, with long-term overall and event-free survival below 50%." (PMID 29515255, 2018). "To determine the mechanism by which miR-665 inhibited neuroblastoma cell proliferation, we investigated the effects of miR-665 on HDAC8 and c-MYC expression." (PMID 30237861, 2018). "We found that miR-665 directly targets the cMYC and HDAC8 3’-UTRs, inhibiting their expression and reducing mouse neuroblastoma cell growth." (PMID 30237861, 2018). "HDAC8 plays a role in neuroblastoma pathogenesis, and HDAC8 overexpression was correlated with advanced neuroblastoma stage and metastasis." (PMID 30237861, 2018). "It is conceivable that activation of this pathway mediates the HDAC8 inhibitor-induced priming of neuroblastoma cells for neurite extension and branching." (PMID 29515255, 2018). "Here, we used a kinome-wide RNAi screen to identify new combinations that enhance the sensitivity of neuroblastoma to HDAC8 inhibitors." (PMID 29515255, 2018). "This is the first report to show that miR-665 is a suppressor miRNA directly targeting the 3’-UTRs of c-MYC and HDAC8 in neuroblastoma." (PMID 30237861, 2018). "Selective HDAC8 inhibition induces a differentiated phenotype in neuroblastoma and reduces neuroblastoma growth in vitro and in vivo at least as effectively as unspecific HDAC inhibition while displaying fewer adverse effects." (PMID 29947893, 2018). "Using HDAC8-dependent neuroblastoma tumor models, we previously demonstrated that inhibition of a single HDAC isotype is more effective and less toxic than unspecific HDAC inhibition." (PMID 29515255, 2018). "Bt2cAMP also upregulated miR-665, and miR665 transfection mimicked the effects of Bt2cAMP, including reduced c-MYC and HDAC8 expression, increased caspase 3 activation, and reduced neuroblastoma cell growth." (PMID 30237861, 2018). "Although HDAC8 has been shown to promote growth of numerous cancer types and contribute to poor prognosis in childhood neuroblastoma, the molecular actions of HDAC8 in cancer remained poorly defined." (PMID 27283490, 2017). "The expression of HDAC8, a specific protein within the family, correlates with advanced disease and poor outcome in neuroblastoma." (PMID 26771642, 2016). "We demonstrated that HDAC8 inhibits neuroblastoma cell differentiation and HDAC10 promotes autophagy-mediated neuroblastoma cell survival." (PMID 27572323, 2016). "Next, we determined the in vivo efficacy of HDAC8-selective inhibition in neuroblastoma xenograft mouse models." (PMID 25695609, 2015). "To confirm HDAC8 as a potential therapeutic target in vivo, we examined the influence of HDAC8 knockdown on tumor growth in a neuroblastoma xenograft mouse model." (PMID 25695609, 2015). "We have previously demonstrated that HDAC8 depletion of neuroblastoma cells via siRNA transfections resulted in an upregulation of markers for differentiation (NEF and NTRK1) as well as G0/G1 cell cycle arrest with p21WAF1/CIP1 upregulation." (PMID 25695609, 2015). "HDAC8 expression levels significantly correlated with INSS (International Neuroblastoma Staging System) stage 4 and poor overall survival." (PMID 25695609, 2015).
neuroblastoma (continued). "So far, these results point towards HDAC8 as a promising and selective target for neuroblastoma treatment." (PMID 25695609, 2015). "The treatment of a panel of MYCN-amplified as well as MYCN-single-copy neuroblastoma cell lines with HDAC8 inhibitors for 6 days significantly decreased cell numbers." (PMID 25695609, 2015). "We have previously identified HDAC family member 8 (HDAC8) as a novel target in childhood neuroblastoma." (PMID 25695609, 2015). "To determine the in vivo efficacy of HDAC8-selective inhibitors in neuroblastoma, we started to characterize the inhibitors for in vivo use." (PMID 25695609, 2015). "Our experiments also focused on the understanding of the molecular function of HDAC8 in neuroblastoma to find rationally targeted treatment combinations for clinical application of HDAC8-selective inhibitors." (PMID 25695609, 2015). "Knockdown of HDAC8 initiates neuronal differentiation such as an outgrowth of the neurite-like structure in human neuroblastoma cell lines." (PMID 23606881, 2013). "Thiol-based HDAC6 inhibitors, such as compound St.24, underscored notable potency and selectivity with potentially improved pharmacokinetics, while sulfur-containing derivatives like compound St.28 showed HDAC8 selectivity and in vivo antitumor efficacy in neuroblastoma models." (PMID 41440016, 2025). "Furthermore, inhibiting HDAC8 with selective HDAC8 inhibitors or siRNA-mediated knockdown reduces cell proliferation in cultured neuroblastoma cell lines and in vivo using xenograft mouse models." (PMID 38473789, 2024). "Consequently, selective HDAC8 inhibition or degradation is a promising therapeutic strategy in neuroblastoma." (PMID 35886887, 2022). "HDAC8 is an important target in several indication areas including childhood neuroblastoma." (PMID 36233076, 2022). "In neuroblastoma, HDAC8 inhibition increases sensitivity to doxorubicin (Dox)." (PMID 36231123, 2022). "Selective inhibition of HDAC8 caused strong anti-neuroblastoma effects without toxicity in xenograft mouse models." (PMID 36233076, 2022). "In addition, the knockdown of HDAC8 in cultured neuroblastoma cells resulted in inhibition of proliferation and induction of cell cycle arrest and differentiation." (PMID 35886887, 2022). "Interestingly, HDAC8 was downregulated in stage 4S neuroblastoma cases, which are known to undergo spontaneous regression." (PMID 33117806, 2020). "Cell cycle arrest in the G0/G1 phase and induction of p21WAF1/CIP1 expression was previously observed in neuroblastoma cells upon HDAC8 silencing, while an increase of cells in G2/M phase of the cell cycle was reported in hepatocellular cancer cells treated with PCI." (PMID 33015043, 2020). "HDAC8 may be the potential drug target for the treatment of minimal residual disease in neuroblastoma and malignancies such as T-cell lymphoma and acute myeloid leukemia." (PMID 31748509, 2019). "Furthermore, we have previously shown that HDAC8 expression is correlated with advanced tumor stage and poor outcome in neuroblastoma patients." (PMID 29515255, 2018). "In this work, the authors showed a correlation between HDAC8 expression and the International Neuroblastoma Staging System (INSS) stages, as well as with the Shimada pathology classification among others, but they were unable to report an association with MYCN amplification status." (PMID 30344930, 2018). "This endorses selective HDAC8 inhibition as a very promising therapeutic option in neuroblastoma." (PMID 29947893, 2018). "By knocking down HDAC8 using siRNA, neuroblastoma cell proliferation decreased." (PMID 26771642, 2016). "Indeed, our data show that a combination of both HDAC8 inhibitor and 13-cis retinoic acid, a currently applied drug in neuroblastoma treatment protocols, strongly enhanced differentiation in cell culture and decreased tumor growth in vivo." (PMID 25695609, 2015).
neuroblastoma (continued). "Compound 2, a linker-less hydroxamate HDAC8 inhibitor, was tested in neuroblastoma cell lines; siRNA knockdown of HDAC8 as well as inhibition with compound 2 induced differentiation by stimulating neuritic-like structural outgrowth and abrogating cell proliferation without apoptosis induction." (PMID 26200462, 2015). "In neuroblastoma, HDAC8 expression was prognostic for an unfavorable outcome." (PMID 26200462, 2015). "In addition, all HDAC8 inhibitors used delayed neuroblastoma population growth and induced the cell-cycle inhibitor p21WAF1/CIP1." (PMID 25695609, 2015). "The HDAC8-selective inhibitor suppressed neuroblastoma cell proliferation." (PMID 23606881, 2013). "HDAC8 is a type I HDAC that is essential for the correct embryonic development and migration of neural crest cells and has been implicated as a key driver of tumorigenesis in the neural crest tumor neuroblastoma in addition to other tumors such as acute myeloid leukemia and breast cancer." (PMID 38030596, 2023). "Furthermore, HDAC8/10 expression is strongly correlated with markers of poor prognosis and overall survival; thus, a dual HDAC8/10 could be beneficial in neuroblastoma therapy." (PMID 36077415, 2022). "Thus, the design of novel HDAC8 inhibitors as potential neuroblastoma therapeutics could be valuable to expand the treatment options for this patient population." (PMID 32318119, 2020). "However, there are very few effective therapeutic options in neuroblastoma that inhibit HDAC8." (PMID 32318119, 2020). "Hence, future studies will elucidate whether indirect effects mediated by one of the potential HDAC8 substrates alter PI3K signaling in neuroblastoma." (PMID 29515255, 2018). "As ALK inhibition by crizotinib abolished the effect of the HDAC8 inhibitor on AKT but strongly inhibited ERK, which resulted in enhanced cell death, we hypothesized that RTK inhibition shifts the HDAC8 inhibitor-mediated differentiation phenotype toward neuroblastoma cell death." (PMID 29515255, 2018). "Similarly, increased HDAC8 levels in neuroblastoma patient tumors correlated with advanced disease." (PMID 30237861, 2018). "Interestingly, neuroblastoma and MPNST arise from the neural crest and thus may play an underlying role in their similar responses to HDAC8 inhibition as compared to other tumor types." (PMID 26200462, 2015). "However, the effects on CREB phosphorylation were rather modest and further experiments are required to unravel completely the link between retinoic acid and HDAC8 inhibitor combination treatment-induced cell death and differentiation mechanism in neuroblastoma." (PMID 25695609, 2015). "Histone deacetylase 8 (HDAC8) is a key enzyme involved in regulating gene expression and tumor development, positioning it as an attractive target for neuroblastoma." (PMID 41720839, 2026). "NORAD upregulates the expression of histone deacetylase 8 (HDAC8) by sequestering its natural inhibitory miRNA miR-144-3p, thereby promoting neuroblastoma cell proliferation, metastasis, and doxorubicin resistance while inhibiting apoptosis and autophagy." (PMID 38891878, 2024). "Subsequently, depletion of HDAC8 downregulates the expression of MDR1 and elevates Dox sensitivity in neuroblastoma cells, while knockdown of miR-137 reverses these effects." (PMID 36231123, 2022). "Clinical analysis has also highlighted the significant correlation between HDAC8 and HDAC10 expression and patient outcome, suggesting their potential utility as predictive biomarkers of therapeutic response to HDACi in neuroblastoma." (PMID 33117806, 2020). "Thus, MYCN, c-MYC, and HDAC8 may each contribute to neuroblastoma tumorigenesis." (PMID 30237861, 2018). "We have previously identified high HDAC8 and HDAC10 expression to correlate with poor outcomes in neuroblastoma and high-grade neuroblastoma, respectively." (PMID 29947893, 2018).
neuroblastoma (continued). "Our present findings indicated that Bt2cAMP treatment inhibited mouse neuroblastoma cell proliferation, increased caspase 3 activity, and decreased c-MYC and HDAC8 levels." (PMID 30237861, 2018). "In conclusion, this report is the first to identify miR-665 as a potent tumor suppressor that directly targets the 3’-UTRs of HDAC8, c-MYC, and MYCN, each of which is involved in neuroblastoma tumorigenesis." (PMID 30237861, 2018). "The small molecule inhibitor of HDAC8, PCI-48012, decreased cell proliferation in neuroblastoma both in vitro and in vivo." (PMID 26771642, 2016). "Similar to T-cell-derived leukemia and neuroblastoma cells, our human and murine-derived MPNST cells exhibited “sensitivity” to HDAC8 inhibition." (PMID 26200462, 2015). "Nevertheless, besides HDAC8, other HDAC family members also control tumor-suppressive functions in neuroblastoma." (PMID 25695609, 2015). "Because we observed induction of differentiation following selective HDAC8 inhibition, we wondered whether it is possible to further enhance the differentiation phenotype via combination with retinoic acid, a differentiating agent currently in use for neuroblastoma therapy." (PMID 25695609, 2015). "Intriguingly, neuroblastoma and MPNST both arise from neural crest cell origins, suggesting a possible role for HDAC8 in progression of these cancers." (PMID 26200462, 2015). "In summary, comprehensive molecular modelling and biological assessments have demonstrated the strong potential of these non-hydroxamate-based HDAC8 inhibitors for treating neuroblastoma." (PMID 41720839, 2026). "HDAC8 and c-MYC play important roles in promoting the growth and spread of neuroblastoma cells." (PMID 37894282, 2023). "Furthermore, miR-665 has been found to activate cell death and increase the number of cells in G1 phase and decrease the cell number in S phase by targeting HDAC8 and c-MYC, reducing the malignancy of mouse neuroblastoma." (PMID 37894282, 2023). "Besides the good HDAC8 degradation effect of CRBN_1e, the PROTAC also exhibited good anti-neuroblastoma activity and showed enhancing of the differentiation phenotype." (PMID 35886887, 2022). "On the other hand, the HDAC8 selective inhibitor, PCI-34051, has been shown to be effective when treated with KPT-2974 or cytarabine in acute myeloid leukemia and crizotinib or retinoic acid in neuroblastoma." (PMID 35955780, 2022). "In the present work, we aimed at the development of bifunctional molecules that potently and selectively degrade HDAC8 in neuroblastoma cells, while not affecting the activity of the other HDAC isozymes." (PMID 35886887, 2022). "For instance, upregulation of HDAC1, HDAC2, and HDAC3 expression correlated with worse survival in patients with gastric and ovarian tumours, and elevated levels of HDAC8 expression in neuroblastoma were related to advanced disease and negative outcomes." (PMID 34395273, 2021). "Overall, the kinome-wide RNAi screen identified the PI3K pathway to be involved in HDAC8 inhibitor-mediated anti-neuroblastoma effects and identified additional druggable RTKs, such as ERBB2 and ALK, as targets to sensitize neuroblastoma to HDAC8 inhibitor treatment." (PMID 29515255, 2018). "We hypothesized that Bt2cAMP inhibited neuroblastoma cell growth by inducing suppressor miRNAs targeting c-MYC and HDAC8." (PMID 30237861, 2018). "HDAC8 protein levels were quantified via ELISA using extracts prepared from neuroblastoma cells transfected with either the negative control siRNA or siRNA-HDAC8." (PMID 30237861, 2018). "Using small-molecule inhibitors, we now demonstrate that selective inhibition of HDAC8 exhibits antineuroblastoma activity without toxicity in two xenograft mouse models of MYCN oncogene-amplified neuroblastoma." (PMID 25695609, 2015). "All neuroblastoma cell lines used were HDAC8 positive, independent of MYCN oncogene amplification status." (PMID 25695609, 2015).